CEACAM1 (CEA cell adhesion molecule 1)
Diseases named in the same sentence as CEACAM1 in open-access papers (continued):
Sharing a sentence is not in itself a finding about the gene and the disease.
tumor (continued). "Previous reports showed that CEACAM1 is down-regulated in many types of tumours, such as colorectal carcinoma, hepatoma, breast carcinoma, renal cell carcinoma and prostate carcinoma." (PMID 23885995, 2013). "CEACAM1 homophilic interactions occur between CEACAM1-positive cancer cells and CEACAM1-positive tumor infiltrating lymphocytes, which are late-effector lymphocytes." (PMID 22778766, 2012). "Another important advantage of CEACAM1-directed therapy is that patient selection would be based on the presence of CEACAM1 on tumor tissue." (PMID 22778766, 2012). "Indirect immunofluorescence analysis of frozen tumor sections, confirmed that tumor nodules formed by 253-NT cells transfected with either wild type or transmembrane domain mutants remained strongly positive for CEACAM1-4S." (PMID 22235309, 2012). "Membranal CEACAM1 (mCEACAM1) expression is downregulated in some types of cancer and its reexpression by tumor cells inhibits in vivo tumor growth, leading to the original definition of mCEACAM1 as a tumor suppressor." (PMID 22291846, 2012). "These exciting results mark anti-CEACAM1 as a potential specific and safe (compartmentalized to the tumor vicinity) novel immunotherapeutic modality." (PMID 22778766, 2012). "In these studies, over-expression of CEACAM1-4L lead to significantly lower growth rates and less tumorigenicity in both in vitro and in vivo models when compared with un-transfected tumor cells." (PMID 20090913, 2010). "Tumor cells transfected with CEACAM1-1L are less tumorigenic, suggesting that the L-form functions as a tumor suppressor gene." (PMID 20525254, 2010). "As observed with other cancer cell lines the tumour markers Ceacam6 as well as Ceacam1 were upregulated in cell line CaCo2." (PMID 21152443, 2010). "Our results showing increased S:L ratio in tumor cells are consistent with antagonistic properties of the two CEACAM1 isoforms." (PMID 21082031, 2010). "As a first step towards understanding the relationship between altered splicing of CEACAM1 transcripts and neoplasia, we decided to examine the expression of CEACAM1 long and short cytoplasmic domain splice variants in a variety of human tissues." (PMID 18507857, 2008). "CEACAM1 also appears to play a critical role in tumor lymphangiogenesis, and can regulate cell migration via interaction with filamin A." (PMID 19077207, 2008). "The present study was undertaken to better understand the relationship between CEACAM1 expression and neoplasia." (PMID 18507857, 2008). "Primary tumours of six animals showed moderate (++) CEACAM1 immunoreactivity and weak (+) L1 immunoreactivity." (PMID 17262079, 2007). "The binding affinity of the scFv E8 is in a range for efficient, in vivo, antigen capture in tumor cells expressing a shared epitope of the CEACAM1, 3 and 5 proteins." (PMID 16504122, 2006). "An intriguing subset of genes in the cornea signature has been studied in tumor metastasis models because these genes encode proteins that regulate cell-cell or cell-matrix interactions (TWIST, MMP10, SERPINB5, THBS1, CEACAM1, C4.4A)." (PMID 16168081, 2005). "The activation of the apoptotic pathway once again proved the anti-tumor effect of CEACAM1 in MM." (PMID 40173324, 2025). "Furthermore, F. nucleatum binds to TIGIT and CEACAM1, inhibiting T-cell cytotoxic activity and protecting tumor cells from immune cell attack." (PMID 41011327, 2025). "Notably, targeting CEACAM1 for selective depletion of Tregs can effectively remove highly suppressive Tregs from the tumor microenvironment, thereby improving the efficacy of immune therapies and providing a novel immune therapeutic strategy." (PMID 41473772, 2025). "In addition, CEACAM1 plays an oncogenic role in MM by inhibiting tumor cell proliferation, invasion and migration, and inducing apoptosis." (PMID 40173324, 2025).
tumor (continued). "Interestingly, RNA expression in tumor tissue was only evident for CEACAM1, MAGEA4, SRC, TPBG, GPA33, and SUB1, with the highest and lowest expression for SRC and MAGEA4, respectively." (PMID 39949781, 2025). "This suggested that the elevated levels of PD1 observed on circulating tumor-associated PBMC may reflect expression on metaclusters M2- and M5-associated cells and in association with CEACAM1." (PMID 38956268, 2024). "A global assessment of CEACAM1, PD1, and PD-L1 was conducted on the exported and re-clustered B cells which identified cell populations that expressed these markers in diseased (tumor and PBMC)-associated samples of both treatment-naive and -resistant patients but not healthy donors." (PMID 38956268, 2024). "F. nucleatum also bound and activated the cell inhibitory receptor CEACAM1 on CEACAM1 + tumor-infiltrating lymphocytes and CEACAM1 + tumor cells, indicating its potential significance in modulating antitumor immunity and aiding the tumor in evading immune cell attack through an additive mechanism." (PMID 38698370, 2024). "The reason for this contradiction may be related to the expression characteristics of CEACAM1 in different tumor tissues (cell membrane-type expression or cytoplasmic expression), but the exact reason is still not very clear." (PMID 39513107, 2024). "Consistent with this, the levels of CEACAM1 were significantly increased on the immDC and mDC in the treatment-resistant tumors; PD-L1 was increased on both treatment-naive and -resistant tumor groups." (PMID 38956268, 2024). "The immunomodulatory function of TIM-3 is based on key interactions with TIM-3 ligands (e.g., galectin-9, phosphatidylserine (PtdSer), and carcinoembryonic antigen-related cell adhesion molecule 1 (CEACAM1)) expressed on tumor cells or antigen-presenting cells." (PMID 38275876, 2024). "CEACAM1, a member of the CEA family, is associated with the activation and apoptosis of neutrophils, while the inhibition of CEACAM1 may reduce tumor progression." (PMID 38029961, 2024). "In addition, we observed the efficacy of radiotherapy combined with immune checkpoint CEACAM1 inhibitors on intracranial glioma in murine models and its impact on anti-tumour immune responses." (PMID 36928507, 2023). "In addition to PDL1, EBVaGCs express higher levels of CD155/PVR, CEACAM1, and galectin-9 mRNAs, which represent known anti-tumor immunity genes that antagonize T cell responses." (PMID 36680216, 2023). "In this study, we downloaded and analyzed data from TCGA, GEO, and HPA databases to compare the differences of CEACAM1 expression between ccRCC tissues and normal samples adjacent to the tumor mass and to investigate the correlation between CEACAM1 expression levels and clinicopathological features." (PMID 36712923, 2023). "Furthermore, the expression level of CEACAM1 was also negatively related to tumor size status, histological grade, and pathological stage." (PMID 36712923, 2023). "Therefore, it is likely that CEACAM1 promotes invasion and progression by interacting with related molecules in the tumor microenvironment." (PMID 36712923, 2023). "Furthermore, it has also been shown that NEO-201 can block the interaction between CEACAM-5 expressed on tumor cells and CEACAM-1 expressed on NK cells to reverse CEACAM-1-dependent inhibition of NK cytotoxicity." (PMID 36991390, 2023). "CEACAM1 overexpression in OSCC can promote tumor growth and invasion through various mechanisms." (PMID 38067304, 2023). "However, our previous study and other groups' studies have suggested that CEACAM1 is a cancer suppressor molecule that inhibits the development of tumor." (PMID 36712923, 2023). "In addition to their inhibitory effects on tumor cells themselves, anti-CEACAM1 antibodies were also reported to promote anti-tumor activity of several immune cell types." (PMID 38077351, 2023).
tumor (continued). "In addition, A combination of radiotherapy with anti-CEACAM1 immunotherapy significantly inhibited the proliferation of murine intracranial glioma, extended the survival time of mice, and even restored anti-tumour immunity in some mice." (PMID 36928507, 2023). "In some cases, a decrease in the expression of CEACAM1 may promote tumor proliferation and metastasis; In other cases, overexpression of CEACAM1 may inhibit tumor proliferation and metastasis." (PMID 37589542, 2023). "Some studies have shown that CEACAM1 has a dual role in growth and metastasis of tumor cells." (PMID 37589542, 2023). "Thus, TIM-3 and CEACAM1 form an axis that can inhibit immune responses and thereby reduce their anti-tumor immunity." (PMID 37567938, 2023). "However, a transfection of PCa cell line DU145 with CEACAM1-L decreased the tumorigenic potential in a xenograft animal model, suggesting that CEACAM1 is a tumor suppressor in PCa." (PMID 37691945, 2023). "In addition to CEACAM-1, three other ligands are expressed on tumor cells, galectin-9, high mobility group box 1 (HMGB1), and phosphatidylserine (PtdSer)." (PMID 37055849, 2023). "Interestingly, CEACAM6 inhibition enhanced the tumor-suppressive T cell function indicating a crosstalk of CEACAM1 with other CEA family members." (PMID 38077351, 2023). "We found that murine tumour growth was inhibited in the radiotherapy group and the anti-CEACAM1 group compared with that in the isotype control group, whereas murine intracranial tumour volume shrank significantly in the combination therapy group with some mice experiencing even tumour dissipation." (PMID 36928507, 2023). "Since CEACAM1 is upregulated under inflammatory conditions the peri-tumor milieu might have already altered basal CEACAM1 expression in those controls." (PMID 38077351, 2023). "Inhibition of NK-mediated cytolysis also occurs by CEACAM-1 (CD66a), expressed on trophoblasts, whereas, CEACAM-1 in tumor cells diminishes expression of NKG2D receptors on NK cells, thus suppressing NK cytolysis implying another common link between cancer and pregnancy." (PMID 35517798, 2022). "However, in advanced disease, CEACAM1 is highly expressed in some types of cancer and correlates with tumor progression." (PMID 36140182, 2022). "While tumor angiogenesis is required for tumor neovascularization, which is in turn essential for tumor spread and growth, the function of CEACAM1 in tumors remains unclear." (PMID 35812245, 2022). "In the current study, our findings suggest that knocking out CEACAM1 can reduce the oxidative stress in HPMVECs and promote cell proliferation in a hypoxic environment, which is contrary to previously published studies that the angiogenesis was promoted by CEACAM1 in tumor cells." (PMID 35812245, 2022). "The expression patterns of CAECAM1, which differ depending on the type of tumor cells and the stage of the disease, as well as the involvement of the protein in various cellular processes, complicate the understanding of the role of CEACAM1 in carcinogenesis." (PMID 36140182, 2022). "In the early stages of CRC, CEACAM1 inhibits tumor cell proliferation." (PMID 36140182, 2022). "Thus, the modulating functions of CEACAM1 determine its significant effect on the processes of tumor immunoresistance; however, the inhibition of T-cell functions mediated by the interaction of CEACAM1 and TIM-3 requires further clarification." (PMID 36140182, 2022). "Evidence suggests that CEACAM1 inhibits NKG2D ligand (NKG2DL) expression in tumor cells." (PMID 36439472, 2022). "In publicly available RNA-seq data, a correlation in immune cancer between TIM-3 and CEACAM1 expression is seen, which is consistent with reports by other groups that have shown an overexpression of both TIM-3 and CEACAM1 on tumor-infiltrating T cells in a variety of different tumors." (PMID 35464394, 2022).
tumor (continued). "NEO-201 can also indirectly enhance anti-cancer activity through the blockade of the interaction between CEACAM-5 expressed on tumor cells and CEACAM-1 expressed on natural killer cells to reverse CEACAM-1-dependent inhibition of NK cytotoxicity or through its binding to human regulatory T cells." (PMID 35804808, 2022). "TIM-3 inhibits cytotoxic T cell activity upon binding to ligands including phosphatidylserine, CEACAM-1, galactin-9, thereby suppressing anti-tumor immunity and promoting tumor escape, and these ligands are members of the h-galactoside-binding protein family that are overexpressed by TNBC cells." (PMID 36612100, 2022). "The binding of TIM-3 to the tumor cell-presented CEACAM1 suppresses T-cell function." (PMID 36140182, 2022). "Transient expression of CEACAM1 by tumor cells and subsequent homophilic interaction with CEA cell adhesion molecule 1 (CEACAM1) on tumor-infiltrating lymphocytes may provide a novel immune escape mechanism in ccRCC." (PMID 33686949, 2021). "The homophilic interactions of CEACAM1, occurring between CEACAM1+ TILs, and CEACAM1+ tumor cells, as well as the interaction of CbpF with CEACAM1 expressed on NK and T cells, may protect tumors from killing by these immune cells in a synergistic mechanism." (PMID 34395310, 2021). "CEACAM1 has been known as a tumor suppressor in various epithelial tumors." (PMID 33686949, 2021). "Therefore, the tumor cell lines were transduced with a construct encoding one of the TIM-3 ligands, CEACAM1." (PMID 34853180, 2021). "Furthermore, the presence of TIM-3+ TILs is positively correlated with the number of CEACAM1+ TILs in tumor microenvironment and CEACAM1 expression in HNSCC tissues." (PMID 34368221, 2021). "CEACAM1 is expressed in many cancers and correlates with tumor progression, metastasis, and OS." (PMID 34943606, 2021). "The impact of F. nucleatum CbpF binding to CEACAM1 on these cells in the tumor microenvironment is unknown." (PMID 34336716, 2021). "Moreover, accumulating studies suggest that CEACAM1 is gradually along tumor development and progression." (PMID 34368221, 2021). "In this case, CEACAM1 expression seems to function as a tumor suppressor." (PMID 34368221, 2021). "In addition to inhibition of the recruitment of TILs to the tumor, F. nucleatum activates the T and natural killer (NK) cells inhibitory receptors TIGIT and CEACAM1, leading to a reduction in their ability to kill tumor cells." (PMID 34395310, 2021). "Therefore, the Tim-3/CEACAM1 interaction in the tumor microenvironment is very complex and further exploration of the underlying molecular mechanisms is needed to elucidate the regulatory mechanism." (PMID 33868234, 2021). "Interestingly, cell adhesion molecules CEACAM1/M6/M5, which are considered biomarkers of tumor progression and metastasis, showed low expression levels in LA-treated cells relative to 13-HPODE-treated cells." (PMID 33546321, 2021). "As F. nucleatum is found in several cancer types (including Colon, esophageal, pancreatic and breast) it is plausible to hypothesize that CEACAM1 activation by tumor-colonized fusobacteria might suppress anti-tumor immunity and affect disease outcome." (PMID 34395310, 2021). "Importantly, we expect the pro-tumorigenic effect of F. nucleatum to be much stronger in humans because the activity of the NK and few T cells present in the tumor will be further weakened by inhibitory interactions of Fap2 with TIGIT and of CbpF with CEACAM1." (PMID 32591509, 2020). "CEACAM1 has important roles in angiogenesis, regulation of insulin action and immune responses and is crucial in the progression and metastasis of a range of cancers, exerting oncogenic as well as tumor suppressive actions." (PMID 33075095, 2020). "In the current report the tumor suppressive function of CEACAM1 is consistent with this data." (PMID 31481751, 2019). "CEACAM1-4L induced more invasiveness and less tumor growth than CEACAM1-4S." (PMID 31481751, 2019).
tumor (continued). "The differences between CEACAM1-4S and -4L were invasion and tumor growth." (PMID 31481751, 2019). "Thus, CEACAM1 was attributed to be a novel inhibitory receptor on activated NK cells with adverse effects for tumor immunity." (PMID 30871206, 2019). "Furthermore, the heterophilic interactions of CEACAM5 (often better known as CEA) with CEACAM1 also inhibited the NK cell mediated killing of tumor cells." (PMID 30871206, 2019). "Moreover, we explore the notion that enhanced CEACAM1 cytoplasmic isoform (CEACAM1-4L or CEACAM1-4S) modulates malignant properties such as invasion, lumen formation and tumor growth of gastric cell line." (PMID 31481751, 2019). "These supported our conclusion of the tumor suppressor role of CEACAM1." (PMID 31358815, 2019). "Based on this idea, CEACAM1 basically works as tumor suppressor for cancer." (PMID 31481751, 2019). "The role of CEACAM1 in cancer strongly differs depending on the origin of the tumor cell." (PMID 30050594, 2018). "As no functional lymphocytes are present in scid mice, the observed effect on metastasis (and tumor growth) in this study cannot be T cell-dependent as could be assumed based on a previous study suggesting that CEACAM-1 depletion results in T cell activation." (PMID 30089785, 2018). "Further arguments supporting the molecule's role in tumor growth and progression are revealed by closer insights into the relationship of CEACAM1 with cells of the immune compartment, particularly T and NK cells, which illustrate its capacity to evade the immune system." (PMID 30406153, 2018). "Indeed, full receptor occupancy of CEACAM-1 at a cellular level after in vivo CC1 treatments (30 mg/kg) was demonstrated by flow cytometry staining on CT26 tumor infiltrates using a fluorescence-labeled CC1." (PMID 30349641, 2018). "Therefore, CEACAM1 has been considered a tumor suppressor and a regulator of epithelial cell polarity, and that significant alterations of its expression are features of malignancy." (PMID 30314283, 2018). "Thus, CEACAM1 is an independent prognostic factor for disease recurrence which is qualitatively comparable to prognosis estimation derived from assessment of tumor size ≥5 cm, or the presence of multinodular HCCs." (PMID 30314283, 2018). "This supports the previously postulated hypothesis that the CEACAM1 presence in normal epithelia functions as a tumor suppressor." (PMID 30406153, 2018). "Therefore, further studies using blocking Abs will be required to thoroughly understand the role CEACAM1 in tumorigenesis and anti-tumor responses in vivo." (PMID 30349641, 2018). "In contrast, in poorer differentiated tumor areas, the expression of membranous CEACAM1 is weaker." (PMID 30314283, 2018). "Given that CEACAM1 expression on both immune cells and tumor cells is reported to be upregulated following activation by IL-2 or tumor cell contact, we also investigated whether anti-PD-1 treatment enhances CEACAM1 expression on CD8+ T cells." (PMID 30349641, 2018). "Detailed investigation of the expression patterns of this adhesion molecule in different cancer types is crucial in determining CEACAM1 involvement in carcinogenesis and possible significance of its altered expression in terms of diagnosis, prognosis, and treatment of distinct human neoplasms." (PMID 30406153, 2018). "CEACAM1 is an immunoglobulin-like cell adhesion molecule with a broad range of biological functions that has been frequently described to play a key role during tumor progression in diverse tumor entities." (PMID 30050594, 2018). "In light of conflicting and partially opposing observations regarding the role of CEACAM1 in anti-tumor responses, we endeavored to further characterize CEACAM1 expression combined with evaluation of its potential tumor growth modulating properties using an anti CEACAM mAb." (PMID 30349641, 2018).